MIR646 (microRNA 646)
Synonyms: hsa-mir-646; MIRN646
Gene: MicroRNA gene on chromosome 20 (60,308,474 to 60,308,567, forward strand). Ensembl gene ENSG00000207802.
Diseases named in the same sentence as MIR646 in open-access papers:
MIR646 is named in the same sentence as 1 disease in open-access papers, as found by Europe PMC text mining. Sharing a sentence is not in itself a finding about the gene and the disease. The quoted sentences say what the papers report.
tumour (1 paper, 2022). "The overexpression of many other amplified genes (e.g., AURKA, HRH3, MIR646, MRGBP, PCK1, PMEPA1, SLCO4A1-AS1, SOX18, TNFRSF6B) is associated with PDAC cell proliferation and tumour growth." (PMID 36289850, 2022). "In particular, most of the amplified genes are involved in proliferation and tumour progression in PDAC, such as AURKA, HRH3, MIR646, MRGBP, PCK1, PMEPA1, SLCO4A1-AS1, SOX18, and TNFRSF6B." (PMID 36289850, 2022).